PRMT1 (protein arginine methyltransferase 1)
Diseases named in the same sentence as PRMT1 in open-access papers (continued):
Sharing a sentence is not in itself a finding about the gene and the disease.
leukemia (continued). "KMT2A-GAS7 (MLL-GAS7) or KAT6A-NCOA2 (MOZ-TIF2) AML mouse models reveal that the recruitment of PRMT1 is necessary but not sufficient for leukemia induction." (PMID 36358861, 2022). "To define the functional involvement of Prmt1 in leukemias, we performed a systematic functional screen by retroviral transduction and transformation assay (RTTA) using validated Prmt1 small hairpin RNAs (shRNAs) on more than ten different MLL and non-MLL oncogenic transcription factors." (PMID 26766589, 2016). "The discovery of the functional crosstalk between PRMT1 and KDM4C in the establishment of an oncogenic transcriptional program in leukemia provides important insights into the molecular functions and underlying mechanisms of these critical PMTs and KMDs in oncogenesis." (PMID 26766589, 2016). "PRMT1 is necessary but not sufficient for leukemia induction by chimeric transcription factors, which also recruit KDM4C, for epigenetic reprogramming." (PMID 26766589, 2016). "Using primary c-kit+ HSPCs from this Prmt1flox/flox Cre-ER mouse for RTTA, we observed an even more prominent suppression of MLL-GAS7 transformed cells both in vitro and in vivo whereby none of the mice developed leukemia upon Prmt1 deletion." (PMID 26766589, 2016). "The recipient mice that received leukemia cells reconstituted with PRMT1WT but not PRMT1E153Q died earlier than those that received leukemia cells reconstituted with empty vector (median survival: Prmt1 KO+PRMT1WT vs Prmt1 KO+PRMT1E153Q was 21 days vs not reached after monitoring for 65 days)." (PMID 39668478, 2025). "Therefore, MS023 could have effects on leukemia that are not mediated by PRMT1." (PMID 39668478, 2025). "Here we provide experimental evidence for the functional involvement and therapeutic potential of targeting PRMT1, an H4R3 methyltransferase, in various MLL and non-MLL leukemias." (PMID 26766589, 2016). "To further demonstrate the in vivo therapeutic potentials of targeting Prmt1 in the clinically relevant setting, we transplanted MOZ-TIF2 leukemia cells carrying UbC-luciferase reporter without any pretreatment into syngeneic mice and then subjected them to AMI-408 treatment." (PMID 26766589, 2016). "Consistently, PRMT1 knockdown increased RBM15 protein level but not the RBM15 mRNA level in MEG-01 cells as well as in other leukemia cells (data not shown)." (PMID 26575292, 2015).
hepatocellular carcinoma (23 papers, 2019 to 2026). A malignant tumor that arises from hepatocytes. "We recently demonstrated protein arginine methyltransferase 1 (PRMT1) is upregulated in hepatocellular carcinoma (HCC) to methylate and activate phosphoglycerate dehydrogenase (PHGDH), thereby promoting serine synthesis." (PMID 38839752, 2024). "In recent years, the role of PRMT1 in the metabolism of hepatocellular carcinoma has been widely discussed." (PMID 38402202, 2024). "PRMT1 has emerged as a significant player in liver cancer, particularly hepatocellular carcinoma (HCC)." (PMID 38326807, 2024). "Mechanistically, activated Smad signaling due to PRMT1 activation fosters EMT through the TGF-β1/Smad pathway in hepatic carcinoma cells." (PMID 38326807, 2024). "In hepatocellular carcinoma cells treated with a PRMT1 inhibitor (AMI-1), the protein expression level of ME2 was significantly downregulated after 72 h of treatment." (PMID 39528487, 2024). "We also used shRNAs to knockdown PRMT1 expression in palmitic acid (PA) treated murine hepatoma Hepa1-6 cells as prototypes to mimic the hepatocytes in HFD-fed mice, and checked the effects on PGC-1α expression, lipid accumulation and FAO." (PMID 35401831, 2022). "Moreover, TK1 appears to contribute to metabolic reprogramming through interaction with PRMT1, as reported in hepatocellular carcinoma, where it promotes glycolysis and tumor aggressiveness." (PMID 41584726, 2026). "Moreover, PRMT1 is highly expressed in T cells and increases the expression of IL-10 and IL-6 to inhibit tumor growth in hepatocellular carcinoma." (PMID 40858547, 2025). "Notably, PRMT1 lactylation at K145 was independently identified in hepatocellular carcinoma lactylome datasets, highlighting evolutionary conservation and pan‐cancer relevance." (PMID 40884268, 2025). "PRMT1-mediated phosphoglycerate dehydrogenase methylation can promote serine accumulation in hepatocellular carcinoma, and can enhance glycolysis in hepatocellular carcinoma cells and promote the progression of liver cancer by methylating thymidine kinase and remodeling the actin cytoskeleton." (PMID 38402202, 2024). "Additionally, PRMT1 is found to promote EMT through the TGF‐β1/Smad pathway in hepatic carcinoma cells, and is required for TGF‐β‐induced Smad3 activation, as well as promoting TGF‐β‐induced EMT." (PMID 37525933, 2023). "It has been reported that the protein level of PRMT1 is upregulated in hepatocellular carcinoma (HCC) to promote tumor progression, and its high level correlates with poor clinical outcomes in HCC patients." (PMID 38839752, 2024). "In the previous experiments we observed that in hepatocellular carcinoma, ME2 interacts with PRMT1 and plays a role in the growth and invasive metastasis of HCC cells." (PMID 39528487, 2024). "Next, we investigated whether the regulation of ME2 by PRMT1 contributes to hepatocellular cancer." (PMID 39528487, 2024). "In human hepatocellular carcinoma (HCC), PRMT1 expression is positively correlated with both PD-L1 and PD-L2 immune checkpoint expression." (PMID 36713412, 2022). "Similarly, in hepatocellular carcinoma (HCC), the expression of PRMT1, -5, and -9 has been correlated with disease advancement, suggesting these as potential therapeutic targets." (PMID 39826691, 2025). "In hepatocellular carcinoma (HCC), PRMT1 directly enhances SOX18 transcription by increasing H4R3me2a levels at its promoter, thereby promoting HCC cell proliferation." (PMID 41256732, 2025). "As a result, methylation of STAT3 by PRMT1 activates STAT3-mediated signaling pathways, leading to the progression and metastasis of several cancers, such as GBM and hepatocellular carcinoma." (PMID 38474197, 2024). "PRMT1 knockdown in tumor cells and macrophages in a diethylnitrosamine (DEN)-induced hepatocellular carcinoma (HCC) mouse model generated significant decreases in PD-L1 and PD-L2, resulting in reduced therapeutic efficacy of PD-1 antibody treatment." (PMID 35493527, 2022).
hepatocellular carcinoma (continued). "PRMT1 facilitates the asymmetric di‐methylation of YAP at arginine 124, thereby diminishing the interaction between YAP and LATS1, inhibiting subsequent phosphorylation of YAP, and promoting both YAP activity and cell proliferation in hepatocellular carcinoma." (PMID 39367565, 2024). "Moreover, according to the clinical correlation between tumor tissues and adjacent normal tissues of 73 HCC patients, PRMT1 was highly expressed in HCC and was positively correlated with ME2 methylation and poor clinical prognosis in hepatocellular carcinoma patients." (PMID 39528487, 2024).
colon cancer (21 papers, 2008 to 2025). "In particular, splice variant 2 of PRMT1 has been proposed as a molecular tissue biomarker of unfavorable prognosis in colon cancer." (PMID 40724932, 2025). "We have also generated a specific antibody for human RIP3 R486 methylation and verified that both RIP3 protein methylation and PRMT1 protein in clinical human colon cancer samples was associated with the longer patient survival." (PMID 37005412, 2023). "Consistently, the high expression of PRMT1 protein was associated with the long overall survival of colon cancer patients." (PMID 37005412, 2023). "The induction of necroptosis by targeting PRMT1 will not only cause cancer cell death, but also increase the immune escape of colon cancer cells." (PMID 37005412, 2023). "PRMT1 subtype was reported to be upregulated in colon cancer and it is associated with poor prognosis." (PMID 33208761, 2020). "In colon cancer, the levels of the PRMT1 v1 isoform are clearly associated with clinical and pathological variables." (PMID 29383172, 2017). "The expression of PRMT1 is associated with multiple cancers including colon cancer." (PMID 37005412, 2023). "Though the mRNA level of PRMT1 in colon cancer tissues tended to be higher than that in cancer adjacent tissues, the high PRMT1 expression in the colon cancer tissues was associated with the longer patient survival, supporting a role of PRMT1 in preventing the tumor malignancy." (PMID 37005412, 2023). "Interestingly, the patient survival analysis of TCGA datasets in our study reveals that PRMT1 mRNA level is also positively associated with colon cancer patient life span." (PMID 37005412, 2023). "Data from this study suggest that PRMT1 gene variant v1 expression may be used as a marker of unfavourable prognosis for colon cancer patients." (PMID 19078953, 2008). "We have shown that PRMT1 inhibits the colon cancer immune escape and tumor growth via RIP3 methylation in the mouse colon cancer." (PMID 37005412, 2023). "Our study demonstrate that PRMT1 suppresses colon cancer, which can provide a more comprehensive knowledge of the underlying mechanisms of PRMT1 in cancer progression." (PMID 37005412, 2023). "With the RIP3ADMA antibody, we were able to characterize the protein levels of RIP3 R486 methylation together with PRMT1 in the colon adenocarcinoma tissue chip containing the colon cancer samples from 93 patients." (PMID 37005412, 2023). "In summary, our study reveals a molecular mechanism of necroptosis and colon cancer immunity that is regulated by PRMT1." (PMID 37005412, 2023). "Consistent with our observation of the in vivo treatment response, Ki67 staining showed that PRMT1 depletion or inhibition suppressed proliferation of colon tumor cells." (PMID 33853662, 2021). "In colon cancer, PRMT1 is involved in epidermal growth factor receptor methylation during the resistance to cetuximab treatment." (PMID 34155784, 2021). "Enhanced PRMT levels are found in various malignancies and high PRMT1 expression is negatively correlated with survival in colon cancer." (PMID 33575256, 2020). "For example, SMYD3‐mediated AKT methylation at lysine 14 plays pivotal roles in activation of the AKT signaling pathway in breast and colon cancers, and PRMT1‐mediated methylation at arginine 887 of INCENP promotes mitosis of lung and cervical cancers." (PMID 28370702, 2017). "In this study, the expression of PRMT1 mRNA was determined, for the first time, by semiquantitative RT–PCR in 120 colon cancer tissues (for 60 of which paired normal colon mucosa was also examined), 14 adenomas and 24 biopsies of inflamed colon mucosa." (PMID 19078953, 2008). "This is a first attempt to acquire an insight on the possible relation of the expression pattern of protein arginine methyltransferase 1 and colon cancer progression." (PMID 19078953, 2008). "During our study, we examined the expression pattern of protein arginine methyltransferase 1 gene in colon cancer patients." (PMID 19078953, 2008).
colon cancer (continued). "Thus, the protein levels of either RIP3ADMA or PRMT1 are beneficial indicators of colon cancer patients." (PMID 37005412, 2023). "Amongst the pool of PRMT1 variants, two splice variants of PRMT1 (variants v.1 and v.2) were reported to be significantly upregulated in CRC and their overexpression was associated with the nodal status and histological grade of tumors in colon cancer." (PMID 37568815, 2023). "We then examined whether murine PRMT1 is also involved in the colon cancer immunity as a mRIP3 methyltransferase." (PMID 37005412, 2023). "In addition to mRNA level, we show that colon cancer PRMT1 protein is consistently higher in the patients who survive longer." (PMID 37005412, 2023). "Previously, the expression of specific isoforms of PRMT1 variants were shown to be significantly associated with nodal status, TNM stage, and tumor grade, and both PRMT4 and PRMT5 are highly expressed in colon cancer." (PMID 29507670, 2018). "In this study, the possible role of PRMT1 as a new biomarker for colon cancer was examined." (PMID 19078953, 2008). "In addition, a defined number of normal and colon cancer samples were examined by immunohistochemistry using in-house-produced polyclonal antibody (anti-PRMT1 IgG) to determine the localisation of the protein." (PMID 19078953, 2008). "These interactions render circ-PRMT1 a potential mediator of mRNA processing or translational efficiency in critical pathways, providing potential mechanistic insights into its association with advanced TNM stages and poor survival outcomes, similar to splice variant 2 of this gene in colon cancer." (PMID 40724932, 2025). "In addition, it has been revealed that PRMT1 could assist in the reversal of RIP3 necrotic colon cancer immune evasion." (PMID 38326807, 2024). "Thus, PRMT1 can be a tumor suppressor in the necroptotic colon cancer." (PMID 37005412, 2023). "Thus, the known oncogenic functions of PRMT1 are mainly regulated through cancer cell proliferation or apoptosis, while the tumor suppressor function of PRMT1 in colon cancer is likely via the suppression of MDSC inflammation microenvironment by inhibiting necroptosis." (PMID 37005412, 2023). "In addition, the down‐regulation of PRMT1 induces the apoptosis in human colon cancer cells." (PMID 34155784, 2021). "In a model of colon cancer, SMARCA4 and PRMT1 were shown to promote CRC progression cooperatively via EGFR signaling." (PMID 38472198, 2024). "Our study provides insights into the molecular mechanism of PRMT1-mediated RIP3 methylation in the regulation of necroptosis and colon cancer immunity, as well as reveals PRMT1 and RIP3ADMA as the valuable prognosis markers of colon cancer." (PMID 37005412, 2023). "Recently, in colon cancer, we reported that propionate suppresses CRC growth by downregulating protein arginine N-methyltransferase 1 (PRMT1) expression, and PRMT1 reduction induced cell apoptosis by controlling the mTOR pathway." (PMID 34972816, 2022). "After the stratification of colorectal adenocarcinoma patients according to their tumor location, we noticed that patients with colon tumors (122 for DFS and 136 for OS) and overexpression of circ-PRMT1 showed significantly shorter DFS intervals (p = 0.026) and OS intervals (p < 0.001)." (PMID 40724932, 2025). "Furthermore, in LPCAT2 knockout mice (LPCAT2−/−) colon cancer model, we found that LPCAT2−/− mice exhibited more severe lesions, while PRMT1 or SLC7A11 inhibitors delayed the progression." (PMID 38605214, 2024). "Additionally, PRMT1 enhances the transcriptional activity of EGFR, further fostering colon cancer cell proliferation, clonogenicity, and migration." (PMID 38326807, 2024). "As we have shown that human PRMT1 serves as a negative regulator of necroptosis in human colon cancer by methylating RIP3, we are interested in knowing whether murine PRMT1 (mPRMT1) is consistently involved in RIP3 methylation and necroptosis inhibition." (PMID 37005412, 2023).
colon cancer (continued). "Furthermore, we demonstrate that PRMT1 inhibits the necroptosis by methylating RIP3, leading to the anti-tumor immune responses and colon cancer suppression." (PMID 37005412, 2023). "PRMT1 methylates RIP3 to inhibit RIP1-RIP3 complex formation, resulting in the impaired RIP3 phosphorylation and necroptosis activation that builds the beneficial immune microenvironment against colon cancer growth." (PMID 37005412, 2023). "In addition, we show that the protein levels of PRMT1 and RIP3 methylation serve as the molecular markers of colon cancer prognosis." (PMID 37005412, 2023). "Moreover, the methylation-deficiency RIP3 mutant promoted necroptosis, immune escape and colon cancer progression due to increasing tumor infiltrated myeloid-derived immune suppressor cells (MDSC), while PRMT1 reverted the immune escape of RIP3 necroptotic colon cancer." (PMID 37005412, 2023).
neuroblastoma (17 papers, 2012 to 2025). Neuroblastoma (NB) is the most common solid, extracranial childhood tumor. "Thus, it is conceivable that the loss of protein ArgMet is associated with loss of PRMT1 expression/activity under physiological conditions, as demonstrated by a recent study linking PRMT1 downregulation with senescence of neuroblastoma cells." (PMID 35475236, 2021). "Interestingly, six genes ARMC6, DCTPP1, EIF4G1, ELOVL6, FBL and PRMT1 were associated with the clinical overall survival of neuroblastoma in both TARGET and GSE85047 datasets." (PMID 32593299, 2020). "Therefore, the increased mobility of the SK-N-SH neuroblastoma cells after PRMT1 knockdown might be specific to the cell line and associated with the significantly increased PAI-1 levels." (PMID 30741995, 2019). "These groups went on to use these systems to investigate metabolic reprogramming in neuroblastoma and the roles of PRMT1 and PES1 in neuroblastoma cell survival." (PMID 40874091, 2025). "Downregulation of PRMT1 in neuroblastoma leads to decreased expression of H4R3me2a enrichment at ATF5 promoter and inhibits tumor cell growth." (PMID 37143582, 2023). "Downregulation of PRMT1 expression in neuroblastoma results in reduced activity of the prosurvival factor ATF5 and inhibits tumor cell growth." (PMID 37143582, 2023). "ATF5 is significantly down-regulated in PRMT1-depleted cells, and the over-expression of ATF5 can rescue the neuroblastoma cells from PRMT1 depletion-induced apoptosis." (PMID 35806136, 2022). "Some examples include inhibiting PRMT1/ATF5 in neuroblastomas, increasing the level of ATF5 inhibition-related miRNAs in gliomas, targeting the Fis-1/ATF5 axis in metabolic diseases, or targeting ATF5 in diabetes." (PMID 35806136, 2022). "Taken together, our findings shed new insights into PRMT1 signaling pathway, and provide evidence for PRMT1 as an actionable therapeutic target in neuroblastoma." (PMID 32415090, 2020). "In good agreement with previous studies, we observed in multiple and diverse PRMT1-depleted human neuroblastoma cell lines an increase of sDMA levels along with the expected decrease of aDMA levels, with no detectable change of PRMT5 protein level." (PMID 32415090, 2020). "Our results indicate a prosurvival role of PRMT1 in a panel of human neuroblastoma cell lines comprising of major phenotypically divergent cell types." (PMID 32415090, 2020). "Collectively, our results reveal that PRMT1-depdenent survival pathway provides potential druggable targets for neuroblastoma." (PMID 32415090, 2020). "Upon the addition of doxycycline (Dox), PRMT1 was efficiently depleted in MYCN-amplified human neuroblastoma cell line Kelly, as demonstrated by western blot in two independent shPRMT1 constructs-transduced cells." (PMID 32415090, 2020). "Further dissection of downstream signaling events of PRMT1 is needed to fully reveal the multifaceted complexity of this epigenetic factor as a regulator of neuroblastoma." (PMID 32415090, 2020). "We further showed that diamidine-related PRMT1 inhibitors displayed anti-neuroblastoma effects both in cell culture and in tumor-bearing mice." (PMID 32415090, 2020). "Here we present evidence supporting an essential function of PRMT1-mediated survival pathway in neuroblastoma." (PMID 32415090, 2020). "To understand how PRMT1 regulates neuroblastoma cell behavior, we first evaluated effects of PRMT1 depletion on cell cycle progression." (PMID 32415090, 2020). "Knockdown of PRMT1 in mouse Neuro2a neuroblastoma cells also greatly reduces the percentage of neurite-bearing cells." (PMID 30741995, 2019). "In our study, we used the S-type neuroblastoma cell line SK-N-SH to investigate the roles of PRMT1 in neuroblastoma." (PMID 30741995, 2019).